CCDC154 (coiled-coil domain containing 154)
Synonyms: C16orf29; LOC645811
Tractability: Antibody: the Human Protein Atlas places it where antibodies can reach.
Gene: Protein-coding gene on chromosome 16 (1,434,383 to 1,444,556, reverse strand). Ensembl gene ENSG00000197599.
Subcellular location: Early endosome
Subcellular location (Human Protein Atlas): Plasma membrane; Golgi apparatus
Gene Ontology:
Biological process: bone mineralization involved in bone maturation
Cellular component: early endosome
Genetic constraint (gnomAD): Loss-of-function variants: 91 observed, 79.3 expected, observed/expected ratio (o/e) 1.15, 90% interval 0.97 to 1.37. The upper end of that interval is the gene's LOEUF score, 1.37, which puts it in group 5 of 6, group 1 being the genes least tolerant of losing a copy. Missense variants: 903 observed, 829.98 expected, observed/expected ratio (o/e) 1.09, 90% interval 1.03 to 1.15. Synonymous variants: 418 observed, 374.21 expected, observed/expected ratio (o/e) 1.12, 90% interval 1.03 to 1.21.
Homologues: Orthologues: chimpanzee CCDC154 (76% identical), rat Ccdc154 (65% identical), mouse Ccdc154 (63% identical), macaque CCDC154 (63% identical), guinea pig CCDC154 (63% identical), dog CCDC154 (54% identical), pig CCDC154 (53% identical).
Diseases named in the same sentence as CCDC154 in open-access papers:
CCDC154 is named in the same sentence as 5 diseases in open-access papers, as found by Europe PMC text mining. Sharing a sentence is not in itself a finding about the gene and the disease. The quoted sentences say what the papers report.
osteopetrosis (2 papers, 2021 to 2022). Osteopetrosis, also known as marble bone disease, is a descriptive term that refers to a group of rare, heritable disorders of the skeleton characterized by increased bone density on radiographs. "In this study, we found that a spontaneous mutation of coiled-coil domain-containing 154 (CCDC154) gene, a new osteopetrosis-related gene, induced congenital deafness in mice." (PMID 33614666, 2021). "Our results indicate that mutation of the osteopetrosis-related gene CCDC154 can induce syndromic hereditary deafness in mice." (PMID 33614666, 2021). "CCDC154 is mainly involved in osteopetrosis and hypoplastic left heart syndrome, and CLCN7 is mainly involved in osteopetrosis and angiogenesis." (PMID 35990977, 2022).
deafness (1 paper, 2021). An inherited or acquired condition characterized by the complete loss of the ability to hear from one or both ears. "The CCDC154 mutant mouse strain exhibits congenital deafness and skeletal abnormalities." (PMID 33614666, 2021).
CCDC154 also shares sentences with these, for which no sentence is quoted: Hearing Loss (1 paper); hypoplastic left heart syndrome (1); tumor (1).